ABCC4 (ATP binding cassette subfamily C member 4 (PEL blood group))
Diseases named in the same sentence as ABCC4 in open-access papers (continued):
Sharing a sentence is not in itself a finding about the gene and the disease.
cancer (72 papers, 2005 to 2026). A tumor composed of atypical neoplastic, often pleomorphic cells that invade other tissues. "ABCC4 (ATP-binding cassette sub-family C member 4) is a transporter protein that is primarily localized to the plasma membrane, and its efflux activity is associated with the progression of various cancers and the development of drug resistance." (PMID 40148998, 2025). "This polymorphism affects the expression of ABCC4 protein on cancer cells through altering the inhibitory role of miR-3190-5p." (PMID 28765596, 2017). "Just recently, a considerable body of evidence indicates that MRP4/ABCC4 is implicated in the development of cancer, supporting its role as a novel therapeutic target." (PMID 25301721, 2014). "Since measurement of the intracellular accumulation level of test drugs is important for understanding the molecular mechanism via which the non-synonymous SNP variants of ABCC4 alter the drug resistance profiles of cancer cells, this investigation is now in progress." (PMID 28677646, 2017). "ABCC4 confer topoisomerase II inhibitor-resistance in macrophages and also serve as a critical member of the multidrug resistance-associated protein subfamily involved in efflux of anticancer/antiviral nucleotide agents inducing resistance to chemotherapy in several kinds of carcinomas." (PMID 24454870, 2014). "In a cohort-based association study involving 111 cancer patients, genotyping of ABCC1/MRP1, ABCC2/MRP2, and ABCC4/MRP4 was conducted using real-time PCR with TaqMan probes." (PMID 41751467, 2026). "The ABCC4 encodes multidrug-resistant protein 4 (MRP4), an ATP-binding cassette C-subfamily transporter expressed in various tissues and cancers, and plays a key role in the pharmacokinetics and pharmacodynamics of multiple drugs." (PMID 40458790, 2025). "In particular, the overexpression of ABCC4 in cancer cells can lead to reduced intracellular drug accumulation, contributing to multi-drug resistance in cancer chemotherapy." (PMID 40149355, 2025). "Cyclic adenosine monophosphate (cAMP) is considered one of the substrates transported by ABCC4 and plays a significant role in the development and progression of various cancers." (PMID 40148998, 2025). "The results presented herein further delve into the functional implications of elevated ABCC4 levels in PDAC by establishing its association with the EMT, a pivotal process in cancer progression, aggressiveness, and resistance to chemotherapy." (PMID 39114357, 2024). "The overexpression of P‐gp (ABCB1), ABCC1 and ABCC4 in K562/FLM cells suggests the classic MDR phenotype observed in many resistant cancer cells." (PMID 39046364, 2024). "In recent years, accumulating evidence has highlighted ABCC4/MRP4 as a promising prognostic marker in various cancers, including PDAC." (PMID 39114357, 2024). "Human MRP4 (hMRP4), encoded by the ABCC4 gene, comprises a single polypeptide of 1325 residues, which was first identified in human cancer cell lines in 19975." (PMID 37217525, 2023). "Our screening results provide strong genetic evidence that the ABCC4 expression level can be used as an important marker for evaluating cancer cells’ response to CPT treatment." (PMID 35869071, 2022). "Numerous studies indicate that the members of the ABC transporter family associated with multidrug resistance (MDR) in cancer cells include p-glycoprotein (P-gp/ABCB1), MRP1/ABCC1, MRP2/ABCC2, MRP4/ABCC4, and BCRP/ABCG2." (PMID 32164712, 2020). "We also found a positive correlation between ABCC4 expression and TGFβ1/2 receptors and its ligand TGFβ2, which were shown to be involved in epithelial conversion induction in cancers." (PMID 33261018, 2020). "It is important to measure the levels of intracellular accumulation of test drugs to understand the molecular mechanisms by which substitution of Gly187 to Trp in ABCC4 alters the drug resistance profiles of cancer cells." (PMID 30634695, 2019).
cancer (continued). "In this paper we propose a novel mechanism by which a long non-coding RNA, PCAT92, drives cancer via regulation of a neighboring gene, ABCC4 on chromosome 13." (PMID 30197753, 2018). "Abnormal expression of ABCC4 has been observed in many cancer cells and is involved in the resistance." (PMID 30643796, 2018). "In the patients with rs3742106 T/T genotype, the expression of ABCC4 on cancer cells is suppressed by miR-3190-5p, thus the efflux of 5-FU is reduced and the sensitivity to 5-FU is enhanced." (PMID 28765596, 2017). "Most studies on ABCC4 have focused on its role in cancer chemotherapy, particularly its ability to confer clinical drug resistance." (PMID 28659663, 2017). "We strongly believe that the present study can improve our understanding of the effect of non-synonymous ABCC4 SNPs on cancer chemotherapy and contribute to the development of novel therapeutic strategies for cancer treatment." (PMID 28677646, 2017). "While in the patients with G/G genotype, ABCC4 is overexpressed on cancer cells and intracellular concentration of 5-FU is decreased, so that the drug resistance is elevated." (PMID 28765596, 2017). "In particular, current evidences suggest that MRP4/ABCC4 is implicated not only in chemotherapy resistance, but also in cancer biology." (PMID 25301721, 2014). "Other lines of evidence also indicate that the SNPs of another ABC gene, ABCC4 (encoding MRP4), showed an association with ADRs induced by cyclophosphamide and methotrexate in cancer patients." (PMID 24734245, 2014). "The chemoresistance property of ABCC4 has been reported in several studies on various carcinomas including CRC." (PMID 24454870, 2014). "Variants in ABC transporter genes, including ABCB1, ABCC4, and ABCC3, as well as solute carrier (SLC) genes such as SLC28A3, are known to influence the pharmacokinetics of numerous anti-cancer agents, including fluoropyrimidines, methotrexate, anthracyclines, and irinotecan." (PMID 40428413, 2025). "ABCC4’s role as a drug transporter, which may also contribute to cancer progression, has been explored in a variety of diseases." (PMID 33081378, 2020). "Importantly, the broad-spectrum resistance in cancer cells is often caused by the overexpression of ABC transporters, and upregulation of ABCC4 transcription is correlated with multidrug resistance in various kinds of cancer." (PMID 33014785, 2020). "ABCC1 (multidrug resistance protein 1/MRP1) and ABCC4 (multidrug resistance protein 4/MRP4) are two members of the C subfamily of ABC transporters that are capable of effluxing several different chemotherapeutic drugs out of cancer cells." (PMID 33081264, 2020). "ABCC4 was among amplified genes in resistant cancer cell lines." (PMID 33334016, 2020). "Since ABCC4 confers drug resistance through the efflux of anticancer drugs from cancer cells, we next determined whether intracellular docetaxel quantity was changed after ERRα manipulation." (PMID 33014785, 2020). "ABCC4 is able to transport a range of organic anionic compounds out of the cell; thus, most functional studies of ABCC4 have classically focused on its role in cancer chemotherapy." (PMID 33261018, 2020). "Since miR-3190-5p, miR-124a and ABCC4 siRNA can inhibit the expression of ABCC4 protein, these small RNAs are observed to increase the intracellular concentration of 5-FU and improve the sensitivity of cancer cells to 5-FU treatment." (PMID 28765596, 2017). "Thus, MRP4/ABCC4 inhibition should be considered as a new alternative strategy for cancer treatment, either alone or in combination with chemotherapeutic drugs." (PMID 25301721, 2014). "However, ABCC1 and ABCC4 can also transport a wide range of substrates involved in inflammation and cellular signaling and have been shown in several different cancer types to have a role in cancer development and progression that is independent of drug resistance." (PMID 33081264, 2020).
cancer (continued). "During the use of ABCC4 inhibitors to reduce chemotherapy resistance or drugs that are potential substrates of ABCC4, the indirect effect on cancer metastasis should be taken into consideration and may be important in selecting a therapy scheme for individual patients." (PMID 33261018, 2020). "Since irinotecan has been reported to be a potential substrate for ABCC4, we reasoned that these drugs, through substrate competition with cAMP, may also elevate intracellular levels of cAMP and increase cell migration and ultimately cancer dissemination." (PMID 33261018, 2020). "The results presented here will improve our understanding of the effects of non-synonymous SNPs in the ABCC4 gene on cancer chemotherapy and could contribute to the development of novel therapeutic strategies as well as diagnostic and therapeutic approaches for cancer chemotherapy." (PMID 30634695, 2019). "Therefore it’s possible that the sensitivity of cancer cells to 5-FU might also be enhanced by miR-3190-5p, which is able to suppress the expression of ABCC4." (PMID 28765596, 2017). "Focusing on ABCC4 gene, two tagSNPs influenced the genetic susceptibility for the development of CRC (rs1751051 and rs1751031), although none of the SNPs in the LD blocks tagged by these two SNPs could explain the altered risk for cancer development." (PMID 24694755, 2014). "ABCC4/MRP4 is an organic anion transporter that mediates cellular efflux of a wide range of exogenous and endogenous compounds such as cyclic nucleotides and anti-cancer drugs; however, it remains unclear whether ABCC4 and its orthologs function in the detoxification of organochlorine pesticides." (PMID 25478949, 2014). "To further investigate the importance of ABC proteins and their engagement in different cancer-related processes, in this manuscript, we decided to compare two CRC subgroups presenting high expression levels of two ABC members: ABCC4 and ABCG2." (PMID 38067326, 2023). "Currently, it is recognized that the main role in multi-drug resistance of cancer cells in vitro is played by ABCB1 (P-gp), ABCC1 (MRP1), ABCC2 (MRP2), ABCC4 (MRP4), ABCG2 (BCRP) and lung resistance protein (LRP)." (PMID 36613834, 2022). "ABCC4 and ABCG2 have the function of excreting UA in the kidney and serve as substrates for the transport of various anti-cancer drugs and environmental carcinogens in various organs." (PMID 36302802, 2022). "Thus, during the use of ABCC4 inhibitors to reduce chemotherapy resistance or drugs that are potential substrates of ABCC4, the indirect effect on cancer metastasis should be taken into consideration and may be important in selecting a therapy scheme for patients." (PMID 33261018, 2020). "Thus, during the use of ABCC4 inhibitors to reduce chemotherapy resistance or drugs that are potential substrates of ABCC4, the indirect effect on cancer metastasis should be taken into consideration and may be important in selecting a therapy scheme for individual patients." (PMID 33261018, 2020). "By mediating nucleotide transport, ABCC4 influences various purinergic signaling pathways, which depending on the local conditions, either inhibits or stimulates cell survival, proliferation, invasion and metastasis in various types of cancer and may lead to an altered expression of HER-2." (PMID 30131693, 2018). "We further performed Q-RT-PCR to determine the mRNA expression levels of ABCA2, ABCC1, ABCC4, ABCD3, and ABCF2, which are the ABC transporters expressed in all of the skin samples in our semi-quantitative RT-PCR, in normal and cancer skin." (PMID 25505559, 2013). "The expression levels of ABCA2, ABCC4, ABCD3, and ABCF2 in human skin were similar between normal and cancer individuals." (PMID 25505559, 2013). "miR-7-5p/ABCC1/SLC7A5, miR-107/RAD51, miR-124-3p/ABCC4/SLC16A1/MGMT, miR-212-3p/ABCG2, miR-381-3p/GJA1 and miR-485-3p/SLC40A1 may modulate pathways that confer chemoresistance to cancer cells." (PMID 40061896, 2025).
cancer (continued). "Regarding PGE2 transporters, there is a lack of information, but SLCO2A1 downregulation and/or ABCC4 overexpression have been found in some cancers." (PMID 33081378, 2020). "ABCC4/MRP4 is an organic anion transporter that mediates cellular efflux of a wide range of exogenous and endogenous compounds such as cyclic nucleotides and anti-cancer drugs; however, it remains unclear whether ABCC4 and its orthologs function in the detoxification and excretion of toxic lead." (PMID 33669601, 2021). "To check whether the ABCC4 expression upregulation is related to the TGFβ signaling pathway in CRC, we analyzed GSE18105 datasets—which represent the statistically most significant differences in EMT markers between normal and cancer cells—for the expression of TGFβ1/2 and their receptors." (PMID 33261018, 2020). "However, it has been proposed that ABCC1 and ABCC4 may play a role in the hallmarks of cancer development and progression, independent of their drug efflux capabilities." (PMID 33081264, 2020). "However recently, because of their ability to transport signaling molecules and inflammatory mediators, it has been proposed that ABCC1 and ABCC4 may play a role in the hallmarks of cancer development and progression, independent of their drug efflux capabilities." (PMID 33081264, 2020). "Studies with ABC transporter-overexpressing carcinoma cell models confirmed that nilotinib effectively reversed ABCB1- and ABCG2-mediated drug resistance, while showed no significant reversal effect on ABCC1- and ABCC4-mediated drug resistance." (PMID 24651611, 2014).
tumor (63 papers, 2007 to 2025). "ABCC4 polymorphisms have mostly been reported to correlate with tumor prognosis and the efficacy of anti-HIV drugs." (PMID 36923356, 2023). "It was shown that the expression of ABCC4 was associated with MYCN amplifications as well as advanced tumor stage." (PMID 32587767, 2020). "Snapshots of three representative samples show tumor-specific increased acetylation and RNA expression of Cyp2c37 and Cyp4a14, encoding Phase I detoxification enzymes, and Abcc4, encoding a bile acid transporter." (PMID 29734330, 2018). "In both studies, ABCC4 expression was associated with MYCN amplification as well as advanced tumor stage." (PMID 23267433, 2012). "The multidrug resistance-associated protein 4 (ABCC4) showed a predominant membrane staining pattern, and was overexpressed in 82.9% (39 of 47 samples) of tumor cases and in 81.25% (13 of 16 samples) of PIN lesions." (PMID 18973659, 2008). "Additionally, our multi-omics analysis proved that the ABCC4 expression correlates with substantially increased tumour-associated macrophage infiltration and sensitivity to FOLFOX treatment." (PMID 38067326, 2023). "We found the proportions and absolute numbers of tumor-infiltrating CD8+ T cells were both elevated upon ABCC4 depletion in RM1 cells." (PMID 39247809, 2024). "To further investigate the specific effects of ABCC4 depletion in tumor cells on the tumor immune microenvironment, we used tSNE plots to indicate the landscape." (PMID 39247809, 2024). "To learn more of the assosiation of ABCC4 expression in tumor cells and T cells, we directly co-cultured stimulated CD8+ T cells with RM1 cells (ABCC4-/- or WT)." (PMID 39247809, 2024). "Bioinformatic analysis on several cohorts including tumor samples, primary patient-derived cultured cells, patient-derived xenografts, and cell lines, revealed a positive correlation between ABCC4 expression and EMT markers." (PMID 39114357, 2024). "We clearly observed c-MYC recruitment to the promoter of ABCC1 and ABCC4 in tumours from Eμ-Myc mice compared with controls that correlate with its higher gene expression." (PMID 35326669, 2022). "Due to the heterogeneity of tissue specimens, it is possible that the expression of ABCC4 in tumor tissues is different, which was higher than that in paired adjacent tissues." (PMID 33946595, 2021). "In an NSCLC study, ABCC4 was highly expressed in tumor cells and tissue and was shown to play a role in cellular proliferation." (PMID 32587767, 2020). "The single-cell sequencing of normal tissues, primary tumors, circulating tumor cells, and metastases, combined with cellular analyses and functional validations, will reveal the role of ABCC4 protein in the diverse responses of CRC patients to therapy." (PMID 33261018, 2020). "A growing body of scientific evidence has demonstrated that both ERRα and ABCC4 are highly expressed in PCa and relate to tumor progression." (PMID 33014785, 2020). "Immunohistochemistry confirmed that ATP binding cassette subfamily C member 4 (ABCC4) proteins were highly expressed in both tumor and adjacent non-tumor liver tissues of patients with high levels of bile acid." (PMID 33225985, 2020). "ERRα and ABCC4 were significantly upregulated in PCa in a data set consisting of 496 tumor vs. 53 normal samples." (PMID 33014785, 2020). "Our results showed a higher level of ABCC4 in the plasma membrane fraction and in EVs from two clones of HT29 cells stably overexpressing Snail, suggesting that the level of ABCC4 expression in CRC determines its functional localization in tumor cells." (PMID 33261018, 2020). "We observed a similar expression pattern of ABCC4 mRNA among the tumor tissues generated from the knockdown cell lines compared to the protein expression of the primary cell lines used for injection." (PMID 28029661, 2017). "The present study provides direct evidence in vivo and in vitro that MRP4/ABCC4 is involved in the regulation of LSCs differentiation as well as in tumor growth and apoptosis." (PMID 25301721, 2014).